MAGEA2 (MAGE family member A2)
Description:
Also represses p73/TP73 activity. Proposed to enhance ubiquitin ligase activity of RING-type zinc finger-containing E3 ubiquitin-protein ligases. Proposed to act through recruitment and/or stabilization of the Ubl-conjugating enzyme (E2) at the E3:substrate complex. May play a role in embryonal development and tumor transformation or aspects of tumor progression. In vitro promotes cell viability in melanoma cell lines. Antigen recognized on a melanoma by autologous cytolytic T-lymphocytes.
Synonyms: CT1.2; MAGE2; MAGEA2A
Gene: Protein-coding gene on chromosome X (152,749,857 to 152,754,145, reverse strand). Ensembl gene ENSG00000268606.
Subcellular location: Nucleus; Nucleus, PML body
Gene Ontology:
Molecular function: DNA-binding transcription factor binding; histone deacetylase binding; protein binding; ubiquitin protein ligase binding
Biological process: cellular senescence; negative regulation of protein acetylation; negative regulation of protein sumoylation; negative regulation of transcription by RNA polymerase II; positive regulation of ubiquitin-protein transferase activity; protein catabolic process
Cellular component: nucleus; PML body
Homologues: Orthologues: chimpanzee MAGEA2 (97% identical), mouse Magea13 (37% identical), rat Magea13 (35% identical), zebrafish ndnl2 (19% identical), Drosophila melanogaster MAGE (16% identical). Paralogues in human: MAGEA2B (100% identical), MAGEA12 (88% identical), MAGEA3 (84% identical), MAGEA6 (84% identical), MAGEA4 (68% identical), MAGEA1 (67% identical), MAGEA8 (63% identical), MAGEA9 (59% identical), MAGEA9B (59% identical), MAGEA11 (59% identical), MAGEA10 (52% identical), MAGEB16 (42% identical), and 25 more.
Diseases named in the same sentence as MAGEA2 in open-access papers:
MAGEA2 is named in the same sentence as 27 diseases in open-access papers, as found by Europe PMC text mining. Sharing a sentence is not in itself a finding about the gene and the disease. The quoted sentences say what the papers report.
melanoma (10 papers, 2011 to 2022). A malignant, usually aggressive tumor composed of atypical, neoplastic melanocytes. "AMPK1 driven-metabolic dis-homeostasis becomes evident by the observed dysregulation of melanoma antigens (MAGEA2/A3/A6), within both these tumor types." (PMID 32293332, 2020). "MAGE-A proteins, including three of the four genes identified in our analysis (MAGEA2, MAGEA3, and MAGEA6), have recently been implicated in resistance to CTLA-4 ICB in melanoma patients." (PMID 32117236, 2020). "However, expression of TDRD9 is not correlated with that of MAGEA1, MAGEA2, MAGEA3, or MAGEA4, which are CTA genes often expressed in lung cancer and melanomas." (PMID 29515758, 2018).
breast carcinoma (3 papers, 2017 to 2023). "In breast cancer, it is verified that overexpression of MAGEA2 and MAGEA3 enhanced the activity of ERα, by which it leads to tamoxifen resistance." (PMID 37857018, 2023). "Moreover, MAGEA2 was identified as molecule involved in tamoxifen-resistant breast cancer." (PMID 36675137, 2023). "MAGEA12 is reported to promote the expression of MAGEA2 and MAGEA3; The higher expression of MAGEA3 is reported to be accompanied by up-regulated expression and activity of ERα, which further leads tamoxifen resistance in breast cancer." (PMID 37857018, 2023). "MAGEA2, MAGEA3, MAGEA4, MAGEA6, and MAGEA12 are up-regulated in the CDKN2A alteration group, amongst which MAGEA3 (HR=1.61[1.27-2.04], p=8.2e-5), MAGEA4 (HR=1.38[1.08-1.77], p=0.011), and MAGEA12 (HR=1.65[1.10-2.48], p=0.015) are accompanied by worse prognosis in breast cancer." (PMID 37857018, 2023).
bladder cancer (2 papers, 2016 to 2024). "A data analysis of bladder cancer patients further uncovers the possibilities of utilizing MAGEA2, MAGEA3, MAGEA4, MAGEA6, MAGEA10, MAGEA11, and MAGEA12 members as diagnostic biomarkers for bladder cancer." (PMID 38254738, 2024). "It was found that frequencies of genomic alterations among MAGEA family members in bladder cancer were MAGEA1 1.8%, MAGEA2 1.6%, MAGEA3 1.9%, MAGEA4 1.6%, MAGEA6 2.6%, MAGEA8 1.7%, MAGEA10 2%, MAGEA11, 2.1%, and MAGEA12 2.4%." (PMID 38254738, 2024). "Interestingly, MAGEA2, MAGEA3, MAGEA4, MAGEA6, MAGEA10, MAGEA11, and MAGEA12 exhibited significant differences in their expression in bladder cancer compared to normal bladder samples." (PMID 38254738, 2024).
colorectal cancer (1 paper, 2025). A primary or metastatic malignant neoplasm that affects the colon or rectum. "We also identified genes with a broad H3K4me3 domain in a specific colorectal cancer cell line but not in normal cells, which could be attributed to intertumoral heterogeneity or a cluster of genes on chromosome X in HCT 116 cells, e.g., MAGE Family Member A2 (MAGEA2)." (PMID 40141189, 2025).
Gynecomastia (1 paper, 2020). Abnormal development of large mammary glands in males resulting in breast enlargement. "MAGEA family members, in particular MAGEA2, MAGEA11, and MAGEC2, showed the hypomethylation of several CpGs (p < 0.01) in MBC compared to gynecomastia." (PMID 32626651, 2020).
pancreatic cancer (1 paper, 2023). "Indeed, our MAGEA DNA vaccine successfully elicits effective T cell activities against each antigen and effectively eliminates GemR tumor cells expressing high levels of MAGEA2, MAGEA3, and MAGEA10 in two distinct mouse models of pancreatic cancer." (PMID 37814317, 2023).
cancer (17 papers, 2006 to 2025). A tumor composed of atypical neoplastic, often pleomorphic cells that invade other tissues. "To gain further insight into the underlying mechanism, we selected MAGEA2 as a representative member to investigate its regulatory role in determining cancer chemoresistance." (PMID 37814317, 2023). "MAGEA2 confers resistance to clinically relevant chemotherapeutic drugs and promotes a phenotype associated with cancer progression." (PMID 28415749, 2017). "To further validate the clinical significance of our findings, we conducted a pan-MAGEA analysis using the KM plotter and TIMER2.0 databases, which includes data from various cancers, summing the expression of MAGEA2, MAGEA3, and MAGEA10." (PMID 37814317, 2023). "MAGEA2, −A3, −A11 and -A12 had lower expression than cancer lines but higher compared to our vector control HEK cells." (PMID 32760472, 2020). "Examples of biclusters from this category include the biclusters consisting of genes from the Cancer-Testis antigens family—MAGEA2, MAGEA3, MAGEA6, MAGEA10, CSAG1, CSAG2, CSAG3 (Xq28)/CT45A3, CT45A5, CT45A6 (Xq26.3)." (PMID 31216036, 2019). "MAGEA2 is overexpressed in various cancers and suppresses the RAS pathway." (PMID 41170329, 2025). "Further mechanistic study reveals that stable MAGEA2-expressing cancer cells highly express GFRAL, while exposure of these cells with CM from Gem treated PSC activate the GFRAL-RET mediated Akt and ERK1/2 dependent cell survival pathway to further enhance their Gem resistance." (PMID 37814317, 2023). "Additionally, three ‘Cancer / Testis‐Antigen’ (CTA) members of the MAGE family were up‐regulated (MAGEA2/3/12; orange labelled)." (PMID 33448076, 2021). "MAGEA2, MAGEA3, MAGEA4, MAGEA6, and MEGEA12, members of the MAGE family, have been studied for their potential for cancer immunotherapy." (PMID 37655157, 2023). "Survival analysis examining high expression levels of three of these genes (UBE2A, MAGEA2 and UTP14A) corresponded with poorer survival in five different cancers." (PMID 31772231, 2019). "The methylation level of the LOH-H cancers was significantly lower at the 5'-transitional CpG sites of the VDR, FLJ43855, CDKN2A, MUC8, MAGEA2, and MSLN genes." (PMID 16827945, 2006). "Our clinical studies have revealed that the expression of MAGEA, particularly MAGEA2, MAGEA3, and MAGEA10, but not other family members, may play a crucial role in determining tumor growth, chemoresistance, and cancer progression in multiple cancers." (PMID 37814317, 2023).
tumor (12 papers, 2009 to 2024). "In this study, we discover that after exposure with the CM of Gem stimulated PSC, it can further enhance MAGEA2-expressing tumor cell resistance to Gem." (PMID 37814317, 2023). "A decrease in tumor necrosis was also observed in Gem treated MAGEA2-expressing tumors compared to the Gem treated VA control tumors." (PMID 37814317, 2023). "Indeed, we show that silencing GDF15 expression in PSC rescues its effect on MAGEA2-mediated chemoresistance in tumor cells." (PMID 37814317, 2023). "Together, these data indicated that Gem stimulated PSCs could regulate the chemosensitivity of MAGEA2-expressing tumor cells via the GDF15-GFRAL mediated paracrine signaling." (PMID 37814317, 2023). "Tumor-specific demethylation was found in GRIN1 (p = 0.005), MAGEA11 (p = 0.001), and MAGEA2 (p = 0.002)." (PMID 19305507, 2009). "The epigenetic reactivation of TKTL1, H19, MAGEA2, MAGEA3/6, MAGEA4, MAGEA11, GPR17, GRIN1, and C19ORF28, genes located at diverse chromosomal loci, occurs simultaneously in individual primary tumors from multiple tumor types." (PMID 19305507, 2009). "To determine whether the protein or metabolite secreted by the Gem stimulated PSC affected the Gem resistance of MAGEA2-expressing tumor cells, we first treated the CM of Gem stimulated PSC with trypsin overnight at 37 °C, and then applied it to the MAGEA2 and VA expressing clones." (PMID 37814317, 2023). "Due to lack of commercially available murine MAGEA2, MAGEA3 or MAGEA10 antibodies, DT6066 and TB32048 (spontaneous KPC tumor derived cells) cells were chronically exposed to Gem until they became resistant." (PMID 37814317, 2023).
MAGEA2 also shares sentences with these, for which no sentence is quoted: lung carcinoma (3 papers); ovarian carcinoma (3); embryonal carcinoma (2); gastric cancer (2); prostate carcinoma (2); renal carcinoma (2); teratocarcinoma (2); arteriosclerosis (1); Cardiovascular Disease (1); glioma (1); hematological cancer (1); infection (1); invasive breast carcinoma (1); metastatic melanoma (1); metastatic tumors (1); myeloma (1); oral squamous cell carcinoma (1); seminoma (1); yolk sac tumor (1).